APLN (apelin)
Diseases named in the same sentence as APLN in open-access papers (continued):
Sharing a sentence is not in itself a finding about the gene and the disease.
cancer (continued). "Moreover, the relationship between the expression of apelin and the role of poly-ADP ribose polymerase (PARP) in carcinogenesis has been demonstrated in studies on several cancer types." (PMID 40076482, 2025). "Unlike other pathways mentioned previously, the apelin signaling pathway (apelin/APJ axis) is involved in the migration of cancer cells, neoangiogenesis, induction of metastases, tumor growth, and proliferation." (PMID 40304310, 2025). "Moreover, in the interaction between cancer cells and macrophages in HNSCC, cancer cells release Apelin peptide, which promotes the polarization of M2 macrophages." (PMID 38650924, 2024). "Pharmacologic targeting of the APLN–APLNR axis can reduce the proliferation and growth of tumor cells, which may be of therapeutic benefit in cancer." (PMID 36614283, 2023). "Functional enrichment analysis showed that mRNAs co-expressed with six lncRNA biomarkers were enriched in many known cancer-related pathways such as the cGMP–PKG signaling pathway, Apelin signaling pathway, Focal adhesion, and transcriptional misregulation in cancer." (PMID 37365153, 2023). "It has been reported that the APLN–APLNR signaling nexus promotes cancer development through several mechanisms, that is, cell proliferation, development of cancer stem cells, drug resistance, and inhibition of cancer cell apoptosis." (PMID 36614283, 2023). "Pharmacologic targeting of the APLN–APLNR axis can reduce the proliferation and growth of tumor cells, which may be of therapeutic benefit in cancers." (PMID 36614283, 2023). "Functional enrichment analysis in our data showed that mRNAs co-expressed with the six lncRNA biomarkers were enriched in many known cancer-related pathways such as cGMP–PKG signaling pathway, Apelin signaling pathway, Focal adhesion and Transcriptional mis-regulation." (PMID 37365153, 2023). "Taken together with our previous reports, it was elucidated that apelin has dual roles in tumor growth, i.e., cancer cell proliferation directly affecting APJ in cancer cells and a cancer-suppressive effect by enhancing tumor immunity through the tumor vasculature." (PMID 36776217, 2023). "Furthermore, according to KEGG pathway analysis, mRNAs were found to be significantly enriched in axon guidance, transcriptional misregulation in cancer, purine metabolism, transforming growth factor-beta (TGF-β) and apelin signaling pathway." (PMID 36200070, 2022). "Therefore, we predicted VEGFA, APLN, and AGT genes as paracrine effectors for the cancer-stroma interaction in KIRCs, whereas DLL4, APP, and TGFB1 genes to be potential autocrine effectors." (PMID 35079698, 2021). "The apelin, APJ and Apela are detected in many types of cancer." (PMID 33912466, 2021). "The Apelin/APJ signaling and Apela may serve as potential therapeutic candidates for treatment of cancer." (PMID 33912466, 2021). "Moreover, the apelin/APJ and Apela/APJ signaling contributed to cancer development and progression, indicating the potential of signaling as therapeutic targets for cancer treatment." (PMID 33912466, 2021). "Notably, the VEGFA, APLN, and AGT genes were more positively expressed in KIRC cancer cells (qVEGFA=1.7×10−4, qAPLN=1.4×10−13, qAGT=6.1×10−7), and showed substantial regulatory effects on downstream genes of the stroma (q." (PMID 35079698, 2021). "Interestingly, the relative expression levels of estimated paracrine effectors, such as VEGFA, APLN, and AGT, were found to be strikingly and significantly higher in PDX cancer components than in cell lines obtained from CCLE data." (PMID 35079698, 2021). "APLN/APLNR signaling has key function in several physiological processes like cardiac function, angiogenesis, metabolism and body fluid homeostasis, and also in pathological conditions like heart failure, cancer, obesity and diabetes (reviewed in detail)." (PMID 31690961, 2020).
cancer (continued). "Moreover, APLN-APLNR signaling is involved in the regulation of multiple human diseases, including heart disease, diabetes, obesity, and cancer." (PMID 31410213, 2019). "Apelin mRNA was detected in clear cell renal cell carcinoma tissue, but there were no significant changes between cancer and normal tissue." (PMID 29875677, 2018). "Although our results need confirmation in a larger patient cohort, this study shows for the first time that APLN expression may be used to predict bvz responsiveness in CRC patients and potentially also for other cancer types." (PMID 28487489, 2017). "Among cancer patients, we as the first ones demonstrated positive correlation between apelin and hsCRP levels and negative correlation between apelin and hemoglobin levels." (PMID 25049439, 2014). "Apelin expression is increased in various kinds of cancer and the apelin/APLNR axis plays a key role in the development of tumours through enhancing angiogenesis, metastasis, cell proliferation and also through the development of cancer stem cells and drug resistance." (PMID 36553076, 2022). "We found apelin exhibiting advantageous effects against atrophy in in vitro models, but not in in vivo models, where we unraveled undesirable apelin resistance that may nullify apelin-based therapy for cancer cachexia." (PMID 35406586, 2022). "The most significantly enriched pathways were apelin signaling pathway, sphingolipid metabolism, hippo signaling pathway, TGF-beta signaling pathway, insulin resistance, tight junction, cellular senescence, transcriptional misregulation in cancers, and lipid metabolism in the TG after TMD." (PMID 36051440, 2022). "Hence, apelin/APJ axis and Apela can be considered as a therapeutic target in treating cancers." (PMID 33912466, 2021). "Compared to apelin, the role of Apela in cancer is not well studied." (PMID 33912466, 2021). "However, CCL8 expression was not different between WT and Apelin-KO mice in other tumor-associated cell types, including the MC38 cancer cells, CD45+ CD31− immune cells and CD45− CD31− stromal cells." (PMID 34234274, 2021). "The increased tumour apelin expression could be a characteristic of highly proliferative cancer cells in more advanced tumours rather than a direct consequence of high circulating apelin." (PMID 32681609, 2020). "A fourth mechanism, quite similar to the previous, could be that as high circulating apelin promote tumour neoangiogenesis, the apelin expression measured in the tumour could originate from proliferating endothelial cells rather than cancer cells." (PMID 32681609, 2020). "Conscious of the fact that examined patients’ tissues contained tumor cells, and also cancer environmental cells; in this stage of study, apelin could not be considered as a biomarker of CRC." (PMID 31547096, 2019). "However, as a tumor vessel maturation inducer, exploiting only the Apelin/APJ axis alone may not be able to cure cancer completely." (PMID 34234274, 2021). "To determine whether upregulation of apelin and its receptor contributes to reduced response to anti-VEGF therapy, we used two different endothelial cell lines (EaHY.926 and b.End3) that endogenously express high levels of APJ compared to normal ovarian epithelial or cancer cells." (PMID 32002127, 2020). "The potential role of resistin, adiponectin, and apelin in in gastroesophageal cancer (GEC) and their influence on cancer progression and cachexia syndrome are not entirely explained." (PMID 25049439, 2014). "Since we could not see any effect on muscle size during cancer cachexia in mice treated with the agonist of APJ, we suspected that apelin could not exert any effects on muscles as in vitro, because APJ could be desensitized in cachectic muscles." (PMID 35406586, 2022).
tumor (131 papers, 2011 to 2026). "We performed RNA-seq analysis on lung tissues and found that S. maltophilia treatment drove inflammation and upregulated tumor associated cell signaling, including Apelin signaling pathway." (PMID 36819033, 2023). "Initially, we suspected that APJ deficiency induced tumor angiogenesis and compensated tumor proliferation that should be observed in the presence of an apelin/APJ system on B16 cells." (PMID 36776217, 2023). "Most studies included in this review examined associations between serum apelin and tumor characteristics such as stage and metastasis." (PMID 36230579, 2022). "With those oncogenes being tightly associated with tumor progression, we next analyzed the cellular function of apelin on these cells." (PMID 36142542, 2022). "Another study has also shown a very weak association of apelin with the tumour histological grade of RCC." (PMID 36553076, 2022). "Many studies also sought to determine associations between apelin and clinical characteristics, most often characteristics of tumor growth and metastasis." (PMID 36230579, 2022). "Here, our clinical exploratory study suggests that tumor expression of apelin in BC is also associated with a poor response to NAC, a factor associated with worse disease-free survival." (PMID 33972642, 2021). "Taken together, it seems that APLN-deficient GBM cells can change their cellular behavior to adhere to the remaining tumor vessels supporting tumor growth by increased invasiveness into the tumor-free brain." (PMID 32545380, 2020). "In models of lung and breast cancer, targeting Apelin prevented resistance associated with anti-angiogenic therapy by reducing tumor growth, metastasis and improving vessel function." (PMID 31690961, 2020). "Here, we observed that APLN -deficiency in the GBM-cells or in the host generates a tumor mass with a reduced vascularization, as compared to tumor with unmodulated APLN levels." (PMID 32545380, 2020). "The APLN/APLNR pathway is upregulated in malignant cells in many tumor types, as well as in tumor endothelial cells, and elevated Apelin levels are associated with disease progression and poor clinical outcome." (PMID 31690961, 2020). "On the other hand, the loss-of-APLN in both GBM cell models in the tumor microenvironment decreased vascular sprouting to a level even lower than the vessel density observed throughout the healthy brain." (PMID 32545380, 2020). "APLN mRNA expression showed weak association to histological grade of the tumour only in the TCGA cohort, in contrast the influence on overall survival showed strong association but failed as an independent predictor." (PMID 30783205, 2019). "In contrast, loss of Apelin reduced the percentage of hypoxic cells adjacent to tumor blood vessels in untreated and, most substantially, in sunitinib‐treated NeuT;Apln−/− tumors." (PMID 31267692, 2019). "While APLN showed only very weak association with tumour histological grade (TCGA cohort), APLNR/mRNA protein expression correlate significantly with ccRCC aggressiveness." (PMID 30783205, 2019). "No signs of an immune response triggered by the allogeneic WJ-MSC-apelin infusion, ectopic tissue formation, or increased levels of tumor-associated antigens were observed in the study." (PMID 30526660, 2018). "High APLN protein expression in tumour tissues was significantly associated with decreased progression-free survival (PFS) in bvz-treated patients (high APLN = 3.8 months, low APLN = 11.06 months, p=0.006)." (PMID 28487489, 2017). "High expression of Apelin in GC cancer samples was associated with poor differentiation, tumor stage, lymph node metastases, and distant metastases." (PMID 27733135, 2016). "Our in vitro study revealed that the Apelin regulated the migration and invasion abilities of GC cell lines, accompanied by up-regulations of a variety of cytokines associated with tumor invasiveness." (PMID 27733135, 2016).
tumor (continued). "We also demonstrate that apelin overexpression in malignant cells is associated with accelerated in vivo tumor growth and with increased intratumoral lymphangiogenesis and lymph node metastasis." (PMID 24962866, 2014). "In cancerous tissues, the loss of crypts was associated with a modified expression pattern of apelin, apelin receptor, and Furin, suggesting that these molecules may play roles in tumor progression and possibly in the tumor microenvironment." (PMID 39962271, 2025). "Although apelin signalling has multifaceted physiological functions, including in the CNS, it is associated with ischaemia as well as neovascularisation events such as retinopathies, tumours, and retinopathies, and a range of neurodegenerative diseases." (PMID 35563075, 2022). "Interestingly, we discovered that high tumor apelin expression was associated with a lower rate of pCR in these patients." (PMID 33972642, 2021). "Furthermore, we found that the loss-of-APLN expression in the tumor microenvironment reduced angiogenesis-dependent tumor growth and increased the survival of GBM-bearing mice." (PMID 32545380, 2020). "Hence, the notoriously low invasiveness that is generally observed with the U87MG cell line seemed to be increased upon loss-of tumor-derived apelin/APLNR signaling." (PMID 32545380, 2020). "Apelin signalling is involved in a broad range of physiological functions and furthermore associated with pathologies that result from decreased vascularisation—for example ischaemia, or neovascularisations events such as tumours and retinopathes." (PMID 32326590, 2020). "In contrast, the loss-of-APLN expression in the tumor cells and the tumor vessels may lead to less functional vessels that finally induce the tumor cells to change their growth behavior." (PMID 32545380, 2020). "By generating subcutaneous xenografts, we found that APLN knockdown in tumor cells, as well as the loss-of-APLN, in the tumor microenvironment significantly reduced VLD by 36% (U87AKDAPLNWT) and 48% (in U87NSCAPLNKO), respectively, as compared to U87NSCAPLNWT controls." (PMID 32545380, 2020). "Apelin has previously been shown to stimulate tumor angiogenesis and is upregulated in tumor‐associated endothelial cells, which we could confirm in endothelial cells isolated from MMTV‐NeuT tumors compared to normal mammary gland (Fig EV2A)." (PMID 31267692, 2019). "Thus, Apelin depletion results in impaired angiogenesis as determined by decreased blood vessel numbers and transcriptome analysis of tumor‐associated endothelial cells." (PMID 31267692, 2019). "Furthermore, high apelin expression was associated with high tumor stage (P < 0.05), distant metastasis (P < 0.05), and vascular invasion (P < 0.05)." (PMID 30984306, 2019). "These levels may reflect the state of vascularisation in these tumours and further underlines the importance of APLN during tumour vascularisation." (PMID 28487489, 2017). "All this suggests that tumour endothelial-derived APLN expression may compensate for bvz-induced loss of VEGF signalling, by fulfilling a comparable pro-angiogenic function." (PMID 28487489, 2017). "By controlling variables related to tumor growth and motility, apelin influences tumor development and metastasis." (PMID 40612675, 2025). "Apelin-dm demonstrates efficacy in inhibiting tumor growth, promoting cell death, suppressing angiogenesis, and early colorectal liver metastasis events." (PMID 39962271, 2025). "The APLN/APLNR system is involved in tumor angiogenesis, and APLNR antagonists have a significant effect on pathological neovascularization diseases." (PMID 41316451, 2025). "Currently, it is considered that apelin supports tumor cell growth and metastasis by enhancing angiogenesis and anti-tumor drug resistance development." (PMID 40227577, 2025). "In vivo studies confirmed that APLN depletion suppressed tumor growth and increased apoptosis, indicating its critical role in cancer progression." (PMID 40740483, 2025).
tumor (continued). "The CD31 and KI-67 staining of tumor sections revealed decreased angiogenic and proliferative indices in apelin-dm-treated mice inoculated by CT-26 and MC-38 tumor cells, respectively." (PMID 39962271, 2025). "Adipocytes produce the polypeptide apelin, which has a variety of biological functions and aids in tumor spreading by encouraging cell proliferation, motility, and survival." (PMID 40612675, 2025). "In vivo tumor growth assay in Rag2/γc mice showed apelin-increased growth, while apelin-dm significantly reduced it." (PMID 39962271, 2025). "Bioinformatics and RNA-Seq analysis revealed that miR-631 directly targets Apelin (APLN), a secreted peptide involved in angiogenesis and tumor progression." (PMID 40429954, 2025). "The anti-tumor effect of apelin-dm was comparable to the effect of the apelin receptor antagonist ML221." (PMID 39962271, 2025). "Among these, while adipocytokine and PPAR signaling are established tumor‐suppressor pathways, apelin signaling typically promotes tumorigenesis." (PMID 40304310, 2025). "Apelin-dm treatment significantly reduced tumor growth compared to controls, as observed in daily monitored tumor volumes for both mice tumor models." (PMID 39962271, 2025). "Limited literature data are available regarding the potential role of other PRAT-derived adipokines (e.g., chemerin, visfatin, omentin-1, and apelin) in kidney pathology and tumor biology." (PMID 40227577, 2025). "The functional analysis revealed that focal adhesion and some important pathways in tumor metastasis were enriched in APLN+ endothelial cells, such as PI3K-Akt signaling pathway and Notch signaling pathway." (PMID 39741182, 2025). "Taken together, these findings suggest that apelin-dm represses tumor growth, angiogenesis, and liver metastasis that are otherwise promoted by apelin." (PMID 39962271, 2025). "According to our study, a capillary endothelial cell subcluster (APLN+) was significantly abundant in both primary tumor and metastatic lymph nodes, indicating the pro-metastatic ability of APLN+ endothelial cells." (PMID 39741182, 2025). "For this reason, inhibitors of the apelin/APLNR axis are currently being investigated as potential antitumoral agents with the ultimate goal of avoiding tumor vascularization." (PMID 41515992, 2025). "Apelin-dm also inhibited tumor growth in syngeneic BALB/c and C57BL/6 mice, using both CT-26 and MC-38 cells." (PMID 39962271, 2025). "Apelin, an emerging systemic factor, assumes a pivotal role in tumor advancement, angiogenesis, and the establishment of a premetastatic niche in potential metastatic organs through its intricate interaction with apelin receptor." (PMID 39962271, 2025). "In the context of malignancies, apelin/APJ has been found to facilitate the maturation of the tumour vasculature and exert a suppressive effect on immune cells." (PMID 39434201, 2024). "Tumour samples exhibiting high APLN expression also show increased capillary dimensions and microvessel quantities." (PMID 39434201, 2024). "Apelin plays a pivotal role in diverse physiological processes, including apoptosis, inflammation, and tumor proliferation, while simultaneously contributing to angiogenesis and cell migration." (PMID 38255203, 2024). "Using KEGG pathway analysis, we have observed that these RyR proteins were involved in several signaling pathways related to tumor biology, including the Apelin signaling pathway, oxytocin-signaling pathway, and calcium signaling pathway." (PMID 39684225, 2024). "In contrast, tumor growth, angiogenesis, and metastasis have been reported to be suppressed in vivo in tumors in mouse models in which apelin expression was suppressed." (PMID 38238841, 2024). "Apelin promotes tumor growth by facilitating endothelial cell migration, resulting in rapid angiogenesis." (PMID 38238841, 2024). "Previous studies have shown that apelin/APJ promoted tumour vascular remodelling, thereby increasing the likelihood of hematogenous metastasis." (PMID 39434201, 2024).